TRBC1 (T cell receptor beta constant 1)
Description:
Constant region of T cell receptor (TR) beta chain. Alpha-beta T cell receptors are antigen specific receptors which are essential to the immune response and are present on the cell surface of T lymphocytes. Recognize peptide-major histocompatibility (MH) (pMH) complexes that are displayed by antigen presenting cells (APC), a prerequisite for efficient T cell adaptive immunity against pathogens. Binding of alpha-beta TR to pMH complex initiates TR-CD3 clustering on the cell surface and intracellular activation of LCK that phosphorylates the ITAM motifs of CD3G, CD3D, CD3E and CD247 enabling the recruitment of ZAP70. In turn, ZAP70 phosphorylates LAT, which recruits numerous signaling molecules to form the LAT signalosome. The LAT signalosome propagates signal branching to three major signaling pathways, the calcium, the mitogen-activated protein kinase (MAPK) kinase and the nuclear factor NF-kappa-B (NF-kB) pathways, leading to the mobilization of transcription factors that are critical for gene expression and essential for T cell growth and differentiation. The T cell repertoire is generated in the thymus, by V-(D)-J rearrangement. This repertoire is then shaped by intrathymic selection events to generate a peripheral T cell pool of self-MH restricted, non-autoaggressive T cells. Post-thymic interaction of alpha-beta TR with the pMH complexes shapes TR structural and functional avidity.
Synonyms: TCRBC1; BV05S1J2.2; TCRB
Gene: T-cell receptor constant (C) gene on chromosome 7 (142,791,694 to 142,793,368, forward strand). Ensembl gene ENSG00000211751.
Subcellular location: Cell membrane
Homologues: Orthologues: mouse Trbc1 (79% identical), mouse Trbc2 (78% identical), rat AC109737.1 (53% identical). Paralogues in human: TRBC2 (97% identical), TRBV24-1 (11% identical), TRBV25-1 (11% identical), TRBV20-1 (10% identical), TRBV19 (10% identical), TRBV27 (10% identical), TRBV29-1 (10% identical), TRBV6-5 (10% identical), TRBV10-1 (9% identical), TRBV10-2 (9% identical), TRBV10-3 (9% identical), TRBV20OR9-2 (9% identical), and 39 more.
Diseases named in the same sentence as TRBC1 in open-access papers:
TRBC1 is named in the same sentence as 26 diseases in open-access papers, as found by Europe PMC text mining. Sharing a sentence is not in itself a finding about the gene and the disease. The quoted sentences say what the papers report.
T-cell lymphomas (20 papers, 2015 to 2026). "In our patient, we observed a TRBC1 monotypic pattern, compatible with the diagnosis of T-cell lymphoma." (PMID 40681778, 2025). "Development of a TRBC2 binder will now allow the possibility of targeting nearly all cases of mature T cell lymphomas, with TRBC1/2 based therapeutics opening the possibility of a widely applicable immunotherapeutic approach in this area of unmet medical need." (PMID 38383515, 2024). "Altogether, these results suggest that TRBC1 expression analysis by FC is a valuable tool for the diagnosis of T-cell lymphomas." (PMID 39796028, 2024). "A recent study has also proposed the inclusion of TRBC1 in a panel for T-cell lymphoma screening, including CD45, CD4, CD2, CD5, TCRγδ, CD7, CD3 and TRBC1." (PMID 40151427, 2024). "Dual TRBC1/TRBC2 transcript expression appears to be more common in T-cell lymphomas (4/13 or 30.8% in our series) than kappa and lambda light chain co-expression in B-cell or plasma cell neoplasms." (PMID 39594145, 2024). "Studies have shown that the assessment of TRBC1 expression by FC can effectively identify monotypic T-cell populations, which is crucial for the diagnosis of T-cell lymphomas." (PMID 39796028, 2024). "One out of thirteen (7.7%) lymphoma samples showed some detectable TCRbeta1/TCRbeta2 protein co-expression, and 4 out of 13 (30.8%) T-cell lymphomas showed a TRBC1/TRBC2 transcript co-expression using BaseScopeTM." (PMID 39594145, 2024). "Multi-parameter flow cytometry detection of TRBC1 expression level can quickly and efficiently diagnose mature T-cell lymphoma, which has good clinical application value." (PMID 36709135, 2022). "An ongoing clinical trial (NCT03590574) is currently investigating the safety and efficacy of a TRBC1-targeting CAR-T therapy named AUTO4 in patients with TRBC1+ T-cell non-Hodgkin lymphoma (T-NHL), PTCL, angioimmunoblastic T-cell lymphoma (AITL), and ALCL." (PMID 34620233, 2021). "T cell lymphomas, however, being clonal, exclusively express either TRBC1 or TRBC2." (PMID 39528665, 2025). "Notably, AUTO4 CAR T cells can deplete healthy TRBC1+ T cells in vitro, albeit less than T cell lymphoma cell lines." (PMID 39528665, 2025). "A clinical trial testing TRBC1 CAR-T cells in T cell lymphomas is ongoing (AUTO4)." (PMID 38225288, 2024). "However, we plan to include this antibody together with TRBC1 in our future T-cell lymphoma FC panels." (PMID 39796028, 2024). "Indeed, polyclonal expression of TRBC1 is improbably found on aberrant T cells in peripheral T-cell lymphomas, thus helping in differential diagnosis." (PMID 40151427, 2024). "A phase I clinical study is now evaluating the safety of this approach against TRBC1+ T-cell lymphomas (NCT03590574), and it could be extended in the near future to T-ALL patients." (PMID 33081391, 2020). "Utilizing this foundational technique, CAR-T trials targeting CD3, CD5, CD7, TRBC1, and CCR4 are ongoing and possess immense potential in the treatment of T-cell lymphomas." (PMID 39456582, 2024). "Here, we present two T cell lymphoma cases, where TCR clonality was evaluated using the TRBC1 monoclonal antibody combined with a multi-parametric staining for an in-depth immunophenotype of physiological and pathological T cell populations." (PMID 40151427, 2024). "Other ADCs and related targeted therapies under investigation for T-cell lymphomas include those targeting CD3, CD70, CD38, and TRBC1." (PMID 39456582, 2024). "The T cell receptor β-chain is expressed in two isoforms, TRBC1 and TRBC2, with clonally expanded mature T cell lymphomas expressing one of them exclusively, while healthy T cells randomly express either TRBC1 or TRBC2." (PMID 38383515, 2024). "TCRβ-chain constant domains 1 and 2 (TRBC1 and TRBC2) are exclusively present on mature T cells while TRBC1 is also expressed in about 50% of TCR+ T-cell lymphomas." (PMID 36624522, 2023).
T-cell lymphomas (continued). "The dysregulation of the mTORC2 pathway is further validated by the observed down-regulation of TCR components (TRAC, TRBC1) and stabilizing molecules (TRAT1) seen across multiple T-cell lymphoma subtypes." (PMID 26566034, 2015). "Among 10 cases of other T-cell lymphomas who had detected all of these three markers, TRBC1 was seen positive in 1 case with CD3 and TCRαβ negative and three cases with CD3 and TCRαβ positive." (PMID 36160159, 2022). "A strategy to target TCRαβ on T cell lymphomas is in trial and relies on discriminatory targeting of TRBC1 or TRBC2, but would not be suitable to combine with CD3ε given their linked multimeric expression." (PMID 34035409, 2021). "All benign samples analyzed (immunohistochemically, by BaseScopeTM, by Q-PCR, and by RNAseq data analysis) had TCRbeta1/TCRbeta2 or TRBC1/TRBC2 ranges well within the previously published flow cytometric benign range (TCRbeta2/TCRbeta1 = 0.18:1–5.7:1), while samples of T-cell lymphoma did not." (PMID 39594145, 2024).
lymphoma (11 papers, 2021 to 2026). A malignant (clonal) proliferation of B- lymphocytes or T- lymphocytes which involves the lymph nodes, bone marrow and/or extranodal sites. "In this study, we analyzed TRBC1 IHC staining in a cohort of benign thymic tissue, thymoma, and T-lymphoblastic leukemia/lymphoma (T-LL)." (PMID 41389353, 2025). "Cytoplasmic TRBC1 immunophenotyping in cases of T-lymphoblastic leukemia/lymphoma correlated with molecular testing for T cell clonality." (PMID 40227608, 2025). "In patients with a TRBC1 PTCL, CAR T cells directed against TRBC1 should target the lymphoma, but spare healthy TRBC2 T cells." (PMID 39528665, 2025). "This study evaluated TRBC1 IHC staining in formalin-fixed paraffin-embedded (FFPE) tissue, encompassing benign thymic tissue, thymomas, and T-lymphoblastic leukemias/lymphomas (T-LL)." (PMID 41389353, 2025). "Intracellular TRBC1 staining by flow cytometry is feasible and might provide useful diagnostic information in the distinction between T lymphoblastic leukemia/lymphoma and benign thymocytes, both of which are mostly negative for surface CD3/TCR complex (manuscript in preparation)." (PMID 33673033, 2021). "T cell leukemias and lymphomas, instead, are either clonally TRBC1 positive or negative." (PMID 38225288, 2024). "A specific subtype diagnosis of lymphoma is possible for many cases with cytology combined with MFC, and more diagnoses on cytology will probably be made with the development of flow cytometric tools such as TRBC1 restriction analysis and molecular techniques such as NGS for mutation detection." (PMID 38805049, 2024). "Second, when performing TRBC1 flow cytometry, it is important to note that the TRBC1 assay is specifically applicable to αβ T cells, with limitations in assessing cells lacking surface TRBC1 or TRBC2 expression, such as γδ T cells, benign thymocytes, and surface CD3− lymphomas." (PMID 40521694, 2025).
angioimmunoblastic T-cell lymphoma (5 papers, 2021 to 2025). A mature T-cell non-Hodgkin lymphoma, characterized by systemic disease and a polymorphous infiltrate involving lymph nodes and extranodal sites. "An ongoing phase I/II clinical trial (NCT03590574) is currently evaluating the safety and efficacy of AUTO4, a TRBC1CAR-T therapy for patients with TRBC1+ TCLs including PTCL, ALCL, and angioimmunoblastic T-cell lymphoma (AITL)." (PMID 36552738, 2022). "LibraT1 is an ongoing phase 1/2 multicenter clinical trial of AUTO4 CAR T cells in TRBC1+ r/r PTCL-not otherwise specified (PTCL-NOS), angioimmunoblastic T cell lymphoma (AITL) and ALCL (NCT03590574)." (PMID 39528665, 2025).
leukemia (4 papers, 2020 to 2023). A malignant (clonal) hematologic disorder, involving hematopoietic stem cells and characterized by the presence of primitive or atypical myeloid or lymphoid cells in the bone marrow and the blood. "On these bases, a recent study focused on the development of third generation anti-TRBC1 CAR T cells, containing CD28 and OX40 co-stimulatory domains, to selectively recognize TRBC1+ cells in vitro and in vivo leukemia models." (PMID 36624522, 2023). "Based on the mutually exclusive expression of TRBC1 and TRBC2, they developed anti-TRBC1 CAR-T cells that recognized and killed normal and malignant TRBC1+ but not TRBC2+ T cells in vitro and in a disseminated mouse model of leukemia." (PMID 35625998, 2022). "They engineered third-generation (CD28 and OX40 costimulatory domains) anti-TRBC1 CAR T cells that were proved to recognized and killed normal and malignant TRBC1+ but not TRBC2+ T cells in vitro, and in a disseminated mouse model of leukemia." (PMID 33081391, 2020).
T-cell neoplasms (4 papers, 2021 to 2025). "As the utilization of TRBC1 staining to detect T-cell clonality continues to expand to many flow cytometry laboratories, more evidence is emerging regarding its high diagnostic and analytical performance, low cost, and applicability to various T-cell neoplasms and specimen types." (PMID 33673033, 2021). "The observed TCR and TRBC1 phenotypes of T-LL are distinct from those of mature T-cell neoplasms and warrant further study." (PMID 41389353, 2025). "We hereby introduce a novel strategy to identify TCRαβ T-cell neoplasms by flow cytometry, based on the restricted expression of TRBC1 or TRBC2." (PMID 38424120, 2024). "The simple measure of TRBC1/TRBC2 could provide a simpler workflow for the identification of T-cell neoplasms." (PMID 40563694, 2025). "Importantly, 9 of the 13 mature T-cell neoplasms with dim TRBC1 expression (69%) were shown to be TRBC2-restricted on dual staining." (PMID 38424120, 2024). "A small subset of TCR α/β-derived T-cell neoplasms show a “TRBC null” phenotype, lacking expression of both TRBC1 and TRBC2." (PMID 41389353, 2025). "In addition, 5 of 38 (13%) mature T-cell neoplasms interpreted as TRBC1-negative on single staining (presumed TRBC2-restricted), were actually negative for both TRBC1 and TRBC2 using dual surface and intracellular staining." (PMID 38424120, 2024).
peripheral T cell lymphoma (3 papers, 2023 to 2025). "Importantly, the established SS PDX model exhibited a stable immunophenotype and expressed several cell surface targets (ICOS, PD-1, TRBC1 and KIR3DL2) that are currently the subject of early clinical investigation in peripheral T-cell lymphoma." (PMID 37718909, 2023).
cutaneous T-cell lymphoma (2 papers, 2021 to 2024). "Interestingly, while in T-PLL (postulated to derive from naïve/central memory cells) TRBC1+ only represented three of 10 (30%) cases investigated, among primary cutaneous T-cell lymphoma (PCTCL)-Sézary syndrome (SS) TRBC1+ cases represented 80% (12 of 15) of the patients, respectively." (PMID 34503189, 2021).
breast carcinoma (1 paper, 2017). "In HR−/HER2+ breast cancer, MMP11 and three i-genes (BTN3A2, CD2, and TRBC1) were significantly associated with clinical outcomes, whereas no clinical variable was significant." (PMID 28409241, 2017). "In HR−/HER2+ breast cancer, four genes (three i-genes BTN3A2, CD2, and TRBC1 and the p-gene MMP11) were significantly associated with distant metastasis-free survival (DMFS)." (PMID 28409241, 2017). "In addition, elevated expression of i-genes (BTN3A2, CD2, and TRBC1) was significantly correlated with favorable clinical outcome in HR−/HER2+ breast cancer, but not in other subtypes." (PMID 28409241, 2017).
chronic myelogenous leukemia (1 paper, 2022). "In addition, sCD3-CD4+ T-CUS was observed in a 58/male chronic myelogenous leukemia patient, a 67/male severe pneumonia patient and an 83/female iron deficiency anemia patient, and TRBC1 was negative for aberrant T cells." (PMID 36160159, 2022).
mycosis fungoides (1 paper, 2021). Classical mycosis fungoides is the most common type of mycosis fungoides (MF), a form of cutaneous T-cell lymphoma, and is characterized by slow progression from patches to more infiltrated plaques and eventually to tumors. "In turn, a frequency of TRBC1+ cases of 50% and 56% was found among PCTCL-mycosis fungoides (MF) (three of six patients) and T-LGLL cases (22 of 39 patients)." (PMID 34503189, 2021).
thymic epithelial tumors (1 paper, 2024). "To confirm this, we evaluated surface and cytoplasmic TRBC1 and TRBC2 expression (T-cell panel) on ten surgical biopsies harboring benign immature T-cell precursors (nine thymic epithelial tumors and one ectopic intrathyroidal thymic tissue)." (PMID 38424120, 2024).
thymoma (1 paper, 2025). A neoplasm arising from the epithelial cells of the thymus. "For all cases of thymic tissue and thymoma, TRBC1 expression was scored as polytypic in the T- cells of interest by both reviewing pathologists." (PMID 41389353, 2025). "All cases of T-LL showed abnormal, “restricted” TRBC1 staining profiles, whereas benign thymic tissue and thymomas demonstrated a polytypic pattern of TRBC1 expression." (PMID 41389353, 2025). "T-LL cases with high tumor burden showed overtly restricted patterns of TRBC1 expression, whereas benign thymic tissue and thymomas consistently showed polytypic staining patterns." (PMID 41389353, 2025). "All thymic tissues (n = 6) and thymomas (n = 5) showed polytypic TRBC1 staining patterns." (PMID 41389353, 2025).
tumor (14 papers, 2015 to 2025). "Higher expression of TRBC1 may indicate preserved cytotoxic T-cell function and enhance tumor cell elimination through ICD-associated adaptive immunity." (PMID 40777132, 2025). "Therefore, targeting TRBC1 can effectively eliminate TRBC1-positive tumor cells, with a loss of approximately 1/3 of the total T cell population." (PMID 35882880, 2022). "In this case, the HuJovi-1 CAR cohort showed significantly lower Jurkat TRBC1 tumor burden in the BM at day 66 compared to KFN CAR cohort." (PMID 38383515, 2024). "In another approach, a drug-conjugated TCR-like antibody (Tesirine, SG3249) against TRBC1 was developed, showing that the antibody was internalized by the tumor cells and killed the cells in vitro and in vivo as demonstrated with immunodeficient mice injected with Jurkat TRBC1+ tumor cells." (PMID 39769267, 2024). "Both TRBC1-restricted and TRBC2-restricted tumors were observed in all disease categories studied, with an overall higher incidence of TRBC2+ neoplasms (73%, 95% CI: 60–83%) as expected by the slight overrepresentation of TRBC2 in the normal T-cell repertoire." (PMID 38424120, 2024). "T and tumor cells were identified by the expression of classic cell type markers, including PTPRC, CD3G, CD3E, TRBC1, and CD8B for T cells and MAGEA 4 for MEL-526 cells." (PMID 33754038, 2021). "CRISPR/Cas9 mediated TRBC1/2 disruption, and lentiviral transduction with a transgenic γδ-TCR, also resulted in a more efficient anti-tumor function of γδ-TCR redirected cells, compared to lentiviral transduction alone." (PMID 32570906, 2020). "As our series is exclusively comprised of T-LL cases with high tumor burden and only contains three patients with positively restricted TRBC1, we feel it is not an ideal cohort to establish/validate diagnostic cutoff points." (PMID 41389353, 2025). "Three novel tumor-derived exosome genes, insulin‐like growth factor binding protein 6 (IGFBP6), VGF (non-acronym), and T-cell Receptor Constant β Chain-1 (TRBC1), which significantly affected the risk score, were also identified." (PMID 36865549, 2023).
cancer (8 papers, 2011 to 2026). A tumor composed of atypical neoplastic, often pleomorphic cells that invade other tissues. "Selective targeting of TRBC1 or TRBC2 enables the killing of cancer cells but preserves about 60-40% of the normal T cells." (PMID 41429932, 2025). "T cell receptor β-chain constant (TRBC) is a promising class of cancer targets consisting of two highly homologous proteins, TRBC1 and TRBC2." (PMID 37753972, 2023). "Even so, this approach will result in substantial TRBC1+ normal T cell depletion and it is as yet unclear whether the residual T cell repertoire will be sufficient to maintain defense against pathogens and/or cancer cells." (PMID 38225288, 2024). "However, the cancer T-cell population exclusively expresses either TRBC1 or TRBC2." (PMID 37753972, 2023). "Among the deregulated proteins, we identified known cancer proteins, such as the tumor suppressors ASS1 and ABI3, which were downregulated in our model, or specifically upregulated TRBC1." (PMID 41715231, 2026). "This permits generation of paired reagents (chimeric antigen receptor-T cells) specific for TRBC1 and TRBC2, with preclinical evidence to support their efficacy in T cell malignancies." (PMID 38383515, 2024). "growth‐proliferation cell cycle‐associated genes such as Myc and Notch1,110 cancer‐associated genes such as Cdkn2a and Alpl, absence of TCR genes such as Trac and Trbc1/2 and elevated RPG expression, a distinct subset of precancerous T cells emerged." (PMID 40887856, 2025).
hematological malignancies (2 papers, 2023). "Additionally, an ongoing clinical trial is examining the safety and efficacy of TRBC1 CAR T-cell therapy for patients with relapsed/refractory TRBC1 positive T-cell hematological malignancies (NCT04828174)." (PMID 36680011, 2023).
TRBC1 also shares sentences with these, for which no sentence is quoted: plasma cell neoplasm (2 papers); acute myeloid leukemia (1); anaplastic large cell lymphoma (1); celiac disease (1); Iron deficiency anemia (1); Lymphoid Tumour (1); multiple myeloma (1); pneumonia (1); Sepsis (1); Sézary syndrome (1); T-cell leukemia (1).